CLEC12A (C-type lectin domain family 12 member A)
Diseases named in the same sentence as CLEC12A in open-access papers (continued):
Sharing a sentence is not in itself a finding about the gene and the disease.
demyelination (1 paper, 2021). "It has been reported that DCs can initiate autoimmune demyelination and inflammation in CNS by presenting antigen to autoreactive myelin-specific T cells, while in the CLEC12A-KO mice the reduction of DC infiltration and demyelination was observed." (PMID 34555062, 2021).
histiocytic sarcoma (1 paper, 2016). An aggressive malignant neoplasm with a poor response to therapy, usually presenting as stage III/IV disease. "Finally, upregulation of GTSF1, LUM, and PYPH and downregulation of CLEC12A and CD9 in primary canine histiocytic sarcomas were found to be dysregulated similarly in 3132 cells." (PMID 27639374, 2016).
Legionella infection (1 paper, 2023). "Currently, the role of CLEC12A in the recognition of L. pneumophila and in the induction of innate immune responses during Legionella infection in vivo is unknown." (PMID 36835297, 2023). "Since L. pneumophila possesses RavZ-dependent and -independent mechanisms to prevent autophagic degradation of intravacuolar bacteria, it is possible that effects of CLEC12A on autophagy are masked by these bacterial mechanisms in the context of Legionella infection." (PMID 36835297, 2023). "Since the role of CLRs in Legionella infection was unknown, here, we screened for CLRs capable of binding the bacterium, and functionally characterized the role of CLEC12A in L. pneumophila infection." (PMID 36835297, 2023).
melanoma (1 paper, 2022). A malignant, usually aggressive tumor composed of atypical, neoplastic melanocytes. "Also, the administration of the drug Tranilast, that suppresses the release of TGF-β by fibroblasts, has been shown to counteract tumor progression in mouse models of C-type lectin domain family 12 member A (CLEC12A/CLL1) Lewis lung cancer and B16F1 melanoma." (PMID 35892828, 2022).
myeloid leukemia (1 paper, 2019). A clonal proliferation of myeloid cells and their precursors in the bone marrow, peripheral blood, and spleen. "Alternatively, more selective tumor antigens have been introduced in TriKE platforms such as C-type lectin domain family 12 member A (CLEC12A), which is highly expressed also on CD33− AML cells and could better contribute to myeloid leukemia targeting by NK cells." (PMID 31623224, 2019).
osteoarthritis (1 paper, 2025). A noninflammatory degenerative joint disease occurring chiefly in older persons, characterized by degeneration of the articular cartilage, hypertrophy of bone at the margins and changes in the synovial membrane. "GSEA using the MSigDB database demonstrated that the GJB2, PAQR5 and CLEC12A genes activate inflammatory-related signaling (NES > 0) and suppress the cholesterol homeostasis (NES < 0), revealing their role in the meniscal degradation process during osteoarthritis progression." (PMID 40724902, 2025).
pneumonia (1 paper, 2023). An acute, acute and chronic, or chronic inflammation focally or diffusely affecting the lung parenchyma, caused by an infection in one or both of the lungs (by bacteria, viruses, fungi, or mycoplasma.). "Moreover, CLEC12A did not influence L. pneumophila-induced pneumonia in mice." (PMID 36835297, 2023).
triple-negative breast carcinoma (1 paper, 2023). An invasive breast carcinoma which is negative for expression of estrogen receptor (ER), progesterone receptor (PR), and human epidermal growth factor receptor 2 (HER2). "In order to confirm this pathway, we overexpressed CLEC12A using a pcDNA 3.1(+) expression vector in both murine 4T1 and human MDA-MB-231 triple negative breast cancer cells." (PMID 38144525, 2023).
urothelial carcinoma (1 paper, 2023). A malignant neoplasm derived from the transitional epithelium of the urinary tract (urinary bladder, ureter, urethra, or renal pelvis). "According to the Human Protein Atlas database, there is a strong correlation between urothelial carcinoma and CLEC12A expression, although the function of CLEC12A in urothelial carcinoma is largely unraveled till date." (PMID 38144525, 2023).
viral encephalitis (1 paper, 2025). Encephalitis resulting from viral infection. "Data revealed that intact CLEC12A signaling in C57BL/6 mice negatively affects effector T cell sequestration in the brain during viral encephalitis." (PMID 41214106, 2025).
tumor (21 papers, 2019 to 2026). "We report that ASGR2 and CLEC12A C-type lectins are associated with tumor-infiltrating immunosuppressive myeloid subsets and discriminate patients' poor prognosis." (PMID 41898489, 2026). "Tumor-associated macrophages (TAMs) further divided into monocyte-derived brain macrophages (Mo-TAMs) expressed monocyte markers (TGFBI, VCAN, LYZ, and CLEC12A) and cells termed as Mg-TAMs expressed microglial signature genes (TMEM119, P2RY12, and P2RY13)." (PMID 39451239, 2024). "Enhanced inflammatory responses promote tumor progression by activating toll-like receptors (TLRs), which in turn are inhibited by C-type lectin like receptors (CTLRs), like CLEC12A." (PMID 38144525, 2023). "The results revealed that the expression of CLEC12A was higher in ALDH+ population of Tumor, TLR4 was higher in ALDH+ population of T+25." (PMID 38144525, 2023). "Tumor-bearing mice were treated with different concentrations of ART and expressions of CLEC12A and associated downstream components were determined." (PMID 38144525, 2023). "Immunoblots were first performed to investigate the expression of CLEC12A in normal mammary fat pad, tumor tissues from untreated tumor-bearing mice and ART-treated tumor-bearing mice." (PMID 38144525, 2023). "Subsequent interaction and modulation of CLEC12A with ART induced tumor cell death and abrogation of CSCs, confirming a more comprehensive tumor therapy with reduced risk of recurrence." (PMID 38144525, 2023). "In AML CDX models, CD19 CAR T cells that secrete CD19-BP–targeting CLEC12A exhibited the similar anti-tumor activity to CLEC12A-targeting CAR T cells." (PMID 36059449, 2022). "However, the expression of CLEC12A reduced upon ART treatment in tumor tissues in a dose-dependent manner." (PMID 38144525, 2023). "In order to validate whether ART treatment downregulates CLEC12A and autophagy to induce apoptosis in tumor cells, cells were treated with the autophagy inhibitor 3-methyladenine (3-MA) followed by treatment with ART in normal and CLEC12A-overexpressed cells." (PMID 38144525, 2023). "Furthermore, on sorting the ALDH- and ALDH+ cells from normal, untreated and ART-treated tumors, it was observed that expression of CLEC12A was higher in ALDH+ cells of the untreated tumor, and reduced in the CSC population after ART treatment." (PMID 38144525, 2023). "Furthermore, we found that gene TTLL5 and CLEC12A have a higher expression on the interactive zone between domains 1 and 5, which may infer their potential relationship with the tumor-immune interaction." (PMID 38844966, 2024). "Therefore, the hypothesis was that inhibition of TLR4 by ART-activated CLEC12A would prevent inflammation and restrain tumor progression, since we observed anti-cancer effects of ART in our primary mice studies." (PMID 38144525, 2023). "For hematologic malignancies, CD33 and CLEC12A (AML), BCMA, and CD38 (MM), and CD30 (PTCL) are targeted as tumor arms." (PMID 36830717, 2023). "This strongly indicated that the anti-proliferative effects of ART were compromised upon CLEC12A over expression, and that downregulation of CLEC12A by ART is a prerequisite for apoptosis of the tumor cells." (PMID 38144525, 2023). "Since TLR4 is known to be suppressed by CLEC12A, the expression of TLR4 was reduced in tumor tissues and gradually increased with ART treatment." (PMID 38144525, 2023). "Many tumor surface antigens are potential targets of BsAbs, such as CD123, CD33, FMS-like tyrosine kinase 3 (FLT3), C-type lectin domain family 12 member A (CLEC12A), and Wilms' tumor gene 1 (WT1)." (PMID 33941237, 2021). "In conclusion, it is inferred that the probability of CD33-directed CAR-T triggering “on-target, off-tumor toxicity” is lower than that of CD123- and CLEC12A-directed CAR-T cells." (PMID 34975912, 2021).
tumor (continued). "Other studies have investigated novel therapeutic strategies to kill AML cells by combination of NK cells, and trispecific killer engager (TriKE) molecules targeting CLEC12A, the AML mice treated with CLEC12A TriKE had significantly less tumor burden compared to tumor alone or tumor with NK cells." (PMID 40726987, 2025). "The paradox was encountered when further in-depth analyses revealed that contrary to our hypothesis, ART significantly downregulated CLEC12A expression, and increased the expression of TLR4 in the presence of ART in tumor tissues." (PMID 38144525, 2023). "This led to the assumption that although ART inhibited expression of CLEC12A, it did not affect the downstream events in a tumor cell via TLR4." (PMID 38144525, 2023). "Concomitantly, ART induced apoptosis of tumor cells, irrespective of the status of TLR4, leading us to assume that ART adopted a non-canonical pathway which differentiated the role of CLEC12A in solid tumors from that known in myeloid cells." (PMID 38144525, 2023). "Unlike CD33, CD123, and CLEC12A, FLT3 off-tumor expression is largely confined to a subset of HSPCs and is much lower than on malignant cells, which may provide a window for targeting AML without profound myeloablation." (PMID 39095991, 2024).
infection (10 papers, 2017 to 2025). The state of being infected such as from the introduction of a foreign agent such as serum, vaccine, antigenic substance or organism. "This interaction suppresses immune responses, as evidenced by enhanced immune reactions in Clec12A-deficient mice after infection, and increased susceptibility in human Clec12A transgenic mice." (PMID 40733653, 2025). "Data show that intact CLEC12A signaling reduces neuroinflammation in C57BL/6 mice following TMEV infection." (PMID 41214106, 2025). "Next, we measured the gene expression and proinflammatory cytokine levels in the lungs of WT and Clec12a−/− mice at 24 h after infection." (PMID 36835297, 2023). "CLEC12A deficiency also activates splenic CD4+ T cells and CD8+ cytotoxic T cells upon infection." (PMID 41214106, 2025). "In conclusion, enhanced T cell recruitment and pro-inflammatory cytokine responses in the brain of CLEC12A−/− mice at the early infection stage suggest a robust immune response, while intact CLEC12A signaling in WT mice is accompanied by impaired virus control following TMEV infection." (PMID 41214106, 2025). "This study shows that absence of CLEC12A prevents S. Typhimurium clearance by HeLa cells and that mice lacking CLEC12A are more susceptible to suffer a more severe infection." (PMID 28293241, 2017). "The study aims to characterize the effect of CLEC12A signaling on virus control and neuropathology in TMEV infection." (PMID 41214106, 2025). "CLEC12A deficiency enhances peripheral immune responses and neuroinflammation, but does not exacerbate hippocampal injury following TMEV infection." (PMID 41214106, 2025). "We thus conclude that CLEC12A is able to bind L. pneumophila but does not play a role in the host’s antibacterial responses to the infection." (PMID 36835297, 2023). "Subsequent functional experiments, however, did not reveal any influence of CLEC12A on the infection of human and murine macrophages by L. pneumophila or antibacterial innate immunity." (PMID 36835297, 2023). "Subsequent infection experiments in human and murine macrophages, however, did not provide evidence for a substantial role of CLEC12A in controlling innate immune responses to the bacterium." (PMID 36835297, 2023). "The infection of bone marrow-derived macrophages (BMDMs) from WT and Clec12a−/− mice with L. pneumophila ΔflaA for over 72 h did not reveal any effect of CLEC12A on bacterial replication." (PMID 36835297, 2023). "Clec12a displayed no significant changes, and Dectin-1 was significantly (p < 0.05) reduced during infection." (PMID 36678402, 2022). "We detected a 2-fold increase in Clec12a (p < 0.01), but a significant decrease in Clec7a (p < 0.001), Clec4b1 (p < 0.0001), and Clec9a (p < 0.001) at D9, further suggesting that Mincle was the preeminent CLR expressed in the lungs during infection." (PMID 34320039, 2021). "On the contrary, an improved integrity of NeuN+ pyramidal neurons and less β-APP+ damaged axons were found in CLEC12A−/− mice, indicating that lack of CLEC12A elicits a protective immune response without amplifying virus-induced immunopathology in the TMEV infection model." (PMID 41214106, 2025).
cancer (9 papers, 2016 to 2025). A tumor composed of atypical neoplastic, often pleomorphic cells that invade other tissues. "The results showed that PTPRC, TLR8, PLEK, NCKAP1L, RGS18 and CLEC12A displayed strong correlation with GPR141 in most cancer types." (PMID 40959105, 2025). "We performed correlation analysis of these six genes (PTPRC, TLR8, PLEK, NCKAP1L, RGS18 and CLEC12A) with GPR141 in pan-cancer." (PMID 40959105, 2025). "Finally, CLEC12A modulation by ART was evaluated in the resident cancer stem cell (CSC) population." (PMID 38144525, 2023). "In pan-cancer, the expression levels of PTPRC, TLRB, PLEK, NCKAP1L, PGS18 and CLEC12A were positively correlated with GPR141." (PMID 40959105, 2025). "The dual nature of CLEC12A has constrained our understanding of this molecule and necessitates further investigation, specifically regarding cancer cells with non-hematopoietic ancestry, for therapeutic benefits." (PMID 38144525, 2023). "This study, for the first time, confirmed a differential role of CLEC12A in non-hematopoietic tumor and cancer stem cells in response to ART." (PMID 38144525, 2023). "Since carcinomas and abnormal findings were not confirmed in the liver, RT-qPCR was performed to examine the expression levels of Glipr1, Clec12a, and Phlda3 in 3-, 6-, 12-, 24-, and 32–34-month-old mouse livers." (PMID 37648885, 2023). "As opposed to reported findings in AML, we showed that cancer stem cells from MDS samples derived from both CLEC12A positive and negative CD34+CD38− subpopulations." (PMID 27612176, 2016).
Bacterial Infections (2 papers, 2021 to 2022). "Together, this suggests that individuals with the AA allele on rs12230244 may be at increased risk of bacterial infection and of developing joint inflammation, acting through reduced induction of CLEC12A expression when exposed to pathogens or other factors inducing IFN signaling." (PMID 35672358, 2022).
infectious disorders (1 paper, 2025). "This indicates that CLEC12A signaling exhibits divergent roles in infectious disorders and may elicit protective and detrimental effects depending on the disease setting." (PMID 41214106, 2025).
CLEC12A also shares sentences with these, for which no sentence is quoted: myelodysplastic syndrome (4 papers); multiple sclerosis (3); experimental autoimmune encephalomyelitis (2); non-Hodgkin lymphoma (2); Allergy (1); Alzheimer disease (1); familial Mediterranean fever (1); fungal infection (1); gastric cancer (1); immune dysfunction (1); inflammation (1); juvenile myelomonocytic leukemia (1); lung carcinoma (1); malnutrition (1); periodontitis (1); peritonitis (1); pulmonary congestion (1); viral disease (1).